DLL1 (delta like canonical Notch ligand 1)
Diseases named in the same sentence as DLL1 in open-access papers (continued):
Sharing a sentence is not in itself a finding about the gene and the disease.
scrub typhus (1 paper, 2024). Scrub typhus is a rare dust mite-borne infectious disease caused by the Orientia tsutsugamushi bacterium and characterized clinically by an eruptive fever which is potentially serious. "Finally, DLL1 plasma levels were associated with a fatal outcome in scrub typhus patients, and ROC analyses revealed that high DLL1 appeared to be a strong marker for short-term survival (AUC of 0.90, p < 0.001) in these patients." (PMID 38502427, 2024). "Thus, the association of DLL1 with adverse outcome in scrub typhus patients could suggest DLL1 is not only a marker, but also a mediator of disease severity in these patients." (PMID 38502427, 2024). "In recovering scrub typhus patients, there was a significant decrease in DLL1 levels compared to admission levels." (PMID 38502427, 2024). "To explore this, we measured plasma levels of DLL1 and the expression of Notch receptors in whole blood of scrub typhus patients." (PMID 38502427, 2024). "Our finding of increased Notch ligand DLL1 in plasma and decreased expression of the receptor Notch4 whole blood in scrub typhus patients was mirrored in vitro in monocytes infected with O. tsutsugamushi." (PMID 38502427, 2024). "Plasma levels of the Notch ligand DLL1 were analyzed in patients with scrub typhus (n = 129), febrile infectious disease controls (n = 31), and healthy controls (n = 31)." (PMID 38502427, 2024). "Levels of DLL1 were markedly higher in scrub typhus patients at admission compared to healthy controls and infectious controls." (PMID 38502427, 2024). "Our main results were: (i) plasma DLL1 was markedly increased in scrub typhus patients at hospital admission with a significant decrease during recovery." (PMID 38502427, 2024). "At baseline, but not at follow-up, high plasma DLL1 at admission was associated with disease severity with significantly higher levels in those with severe scrub typhus comparing those with mild disease." (PMID 38502427, 2024). "Nonetheless, this first report of Notch signaling in scrub typhus patients suggesting that an imbalance between enhanced DLL1 levels and decreased NOTCH4 expression could contribute to the pathogenesis of O. tsutsugamushi infection." (PMID 38502427, 2024). "In contrast to DLL1, NOTCH4 was downregulated in whole blood in scrub typhus patients." (PMID 38502427, 2024). "Thus, high levels of DLL1 and low levels of NOTCH4, as seen in the present study, could potentially contribute to an inflammatory phenotype in scrub typhus patients." (PMID 38502427, 2024).
small cell lung carcinoma (1 paper, 2013). Small cell lung cancer (SCLC) is a highly aggressive malignant neoplasm, accounting for 10-15% of lung cancer cases, characterized byrapid growth, and early metastasis. "DLL1 influence drug resistance of small cell lung cancer through activating transcription of downstream genes HES1 and HEY1." (PMID 23769341, 2013). "Our results suggest that overexpression of DLL1 in small cell lung cancer may increase the sensitivity of cells to chemotherapeutic agents." (PMID 23769341, 2013).
urothelial carcinoma (1 paper, 2014). A malignant neoplasm derived from the transitional epithelium of the urinary tract (urinary bladder, ureter, urethra, or renal pelvis). "Expression of NOTCH1, DLL1 and JAG1 was further analysed by immunohistochemistry in a set of paraffin-embedded tissues covering urothelial carcinomas of all stages and grades." (PMID 25167871, 2014).
Ventriculomegaly (1 paper, 2025). An increase in size of the ventricular system of the brain. "Fetuses with reduced transverse cerebellar diameter and ventriculomegaly should be evaluated for 6q terminal deletions involving DLL1; combining CNV-seq with reflex WES reduces missed diagnoses and informs counseling." (PMID 41190327, 2025).
visceral leishmaniasis (1 paper, 2012). A severe form of leishmaniasis characterized by irregular bouts of fever, substantial weight loss, swelling of the spleen and liver, and anemia (which may be serious). "Interestingly, it was reported recently that within the 6q27 gene cluster, the Dll1 gene was linked to susceptibility to visceral leishmaniasis, and reduced Dll1 expression was measured in VL patients in Sudan, Brazil, and Northen India." (PMID 22396647, 2012).
tumor (88 papers, 2009 to 2025). "DLL3, one of the ligands of the Notch signaling pathway located in the cell membrane of tumor cells, is often expressed in neuroendocrine tumors and exerts an inhibition of DLL1/NOTCH interaction, causing an inhibition of the Notch pathway." (PMID 37893184, 2023). "The expression of Dll1 has been associated with poor prognosis and the tumor-promoting function of Dll1 is exclusive to ERα+ luminal BC, as loss of Dll1 inhibits both tumor growth and invasive potential of luminal BC." (PMID 35682974, 2022). "Collectively, the data implicated that increased DLL1 levels in the TME conferred long-term tumor vascular normalization in a CD8+ T cell- and IFN-γ- dependent manner and enhanced the effectiveness of ICB." (PMID 36439137, 2022). "This decrease in tumor growth and progression was associated with reduced nuclear translocation of NF-kB, suggesting that Dll1-mediated chemoresistance is potentially driven by NF-kB signaling." (PMID 33462238, 2021). "Although less effort has been put in studying other Delta-like ligands’ part in regulating the tumor vasculature, Dll1 has also been reported to be associated with tumor angiogenesis." (PMID 33198378, 2020). "Mice with hetero- or homozygous deletion of Dll1 allele in CD11c+ cells exhibited remarkably accelerated LLC tumor growth and significantly decreased survival compared to their wild-type littermates." (PMID 30940183, 2019). "In search for potential therapeutics to correct insufficiency or deficiency in DC-expressed DLL1-mediated Notch activation pharmacologically, we tested the efficacy of multivalent clustered DLL1 in the setting of DLL1 deficiency in tumor-bearing hosts." (PMID 30940183, 2019). "The fact that loss of even one Dll1 allele produced significantly accelerated disease indicates the importance of DLL1 expression on DCs for tumor rejection." (PMID 30940183, 2019). "To determine if DLL1-deficiency in tumor cells affects lung metastasis, we harvested lungs and acquired bioluminescence signals (BLI)." (PMID 30442981, 2019). "Notch ligands (JAG1-2, DLL1,4), like Notch receptors, showed higher mutations frequencies in tumor cell lines, although these were mainly restricted to the endometrium and prostate cell types." (PMID 25907971, 2015). "Additionally, DLL1 overexpression correlated with the normalization of the tumor immune profile, as it polarized tumor-associated macrophages (TAMs) from an immunosuppressive M2-like phenotype to a proinflammatory M1-like phenotype and activated CD8 + T cells." (PMID 37907742, 2023). "Multivalent clustered DLL1-triggered Notch signaling overcame DC Dll1 deficiency and improved anti-tumor T-cell responses, whereas the pharmacological interference by monomeric soluble DLL1 construct suppressed the rejection of mouse tumors and cardiac allograft." (PMID 30940183, 2019). "As both, NOTCH1 and DLL1, are predominantly localized in more differentiated cells in the normal urothelium, their decreased expression in tumours may conceivably reflect to some extent the loss of this differentiated cell population." (PMID 25167871, 2014). "Finally, Dll1 was implicated in the regulation of tumor angiogenesis in a fibroblast tumor model." (PMID 21923938, 2011). "To date, some researches have demonstrated that IFN-γ can inhibit tumor angiogenesis by downregulating integrin αVβ3, Dll4, Dll1, and vascular endothelial growth factor A (VEGF-A)." (PMID 40370455, 2025). "For instance, DLL1 induces normalization of tumor blood vessels, characterized by sustained improvements in vascular perfusion and reduced hypoxia within the tumor microenvironment." (PMID 41316451, 2025).
tumor (continued). "Notch-related signals activate HES1 through DLL1-Notch1/2-mediated ligand-receptor binding between tumor cells, further regulating the expression of differentiation-inhibitory genes." (PMID 40989695, 2025). "Genetic depletion of Dll1 in CD11c+ murine cells suppressed effector CD8+ T cell activation leading to tumor progression in lung and pancreatic tumors." (PMID 39209451, 2024). "By adding MT- or MTGCSF−/−-CM to the cultures, we found that tumor-derived GCSF was equally potent at blocking cDC1s propagated with DLL1/NOTCH2 signaling." (PMID 36911097, 2023). "Apart from the PI3K/AKT pathway (CDC37, IL6R), Epidermal-Mesenchymal transition (IL6R, SHC2), tumour metastasis and T1/T2 activation are highlighted (DLL1, STAT4, IL6R)." (PMID 36834486, 2023). "The effects of LNT combined with DLL1 on tumor growth were evaluated by growth curve and tumor weight in EO771 breast and LAP0297 lung tumor models." (PMID 36008793, 2022). "Increased DLL1 levels in the TME sensitized anti-cytotoxic T lymphocyte-associated protein 4 (anti-CTLA4) treatment in its resistant tumors, leading to tumor regression and longer survival." (PMID 36008793, 2022). "Although selectively stimulating DLL1/Notch signaling has been shown to suppress tumor growth, only a small part of tumors regressed and most tumors kept growing, just at a relatively slower growth rate." (PMID 36008793, 2022). "We also analyzed the effects of LNT treatments and DLL1 overexpression on tumor-infiltrating immune cells." (PMID 36008793, 2022). "Previous studies showed that IFN-γ mediated the antitumor effects of DLL1 and type I IFNs play a central role in granulopoiesis and promote an anti-tumor phenotype in neutrophils." (PMID 36008793, 2022). "It is striking that LNT treatments induced most of tumor regression in DLL1-overexpressing LAP0297 lung tumor." (PMID 36008793, 2022). "Together, the data suggest that LNT treatments combined with DLL1 overexpression promote the tumor accumulation of CD8+ T cells and CD11b+Ly6G+ neutrophils, as well as the activation of CD8+ T cells in LAP0297 lung tumors." (PMID 36008793, 2022). "We further show that Dll1+ tumor cells are quiescent TICs and Dll1-mediated Notch signaling is one of the major drivers of tumor progression and metastasis in the the MMTV-PyMT model using both reporter and conditional-knockout mouse models." (PMID 33462238, 2021). "We observed a substantial increase in the number of Dll1+ cells as the mammary gland advanced through the hyperplastic stage to the tumor, supporting an oncogenic function Dll1 in PyMT tumors." (PMID 33462238, 2021). "Similar to our in vitro studies, treatment of transplanted Dll1+ and Dll1− tumors with doxorubicin revealed that Dll1+ tumors were resistant, whereas Dll1− tumor growth was significantly impaired upon doxorubicin treatment." (PMID 33462238, 2021). "Together, these data indicate that Dll1 activates NF-kB1 signaling in Dll1+ tumor cells, potentially contributing to protumor survival and associated chemoresistance." (PMID 33462238, 2021). "Blocking of NF-kB activity using the IMD inhibitor in combination with doxorubicin significantly decreased tumor cells viability and stem cells activity in tumorsphere assays, thus phenocopying the effects of the Dll1-blocking antibody." (PMID 33462238, 2021). "We and others have shown that DLL1 contributes to BC tumor biology through the promotion of cancer cell colony formation, cell proliferation, survival, migration, and invasion, BC stem cell (BCSC) function, metastases formation and angiogenesis." (PMID 34439228, 2021). "We next investigated in vivo the ability of Dl1.72 to inhibit tumor growth of human ER+ BC in a MCF-7 xenograft mice model, to address the tumorigenic role of DLL1 in human BCs." (PMID 34439228, 2021). "The dramatic effect of Dll1 deletion on PyMT tumor formation prompted us to investigate the spatial and temporal distribution of Dll1 expression during tumorigenesis." (PMID 33462238, 2021).
tumor (continued). "For this, we generated PyMT-Dll1mCherry reporter mice and evaluated the expression pattern of Dll1+ cells during PyMT-Dll1mCherry tumor progression from normal mammary gland to late-stage tumor." (PMID 33462238, 2021). "Cell cycle analysis further demonstrated a strong increase in a sub-G1 population (apoptotic cells) of Dll1− cells compared to Dll1+ tumor cells." (PMID 33462238, 2021). "To directly test the tumor-initiating function of Dll1, we transplanted sorted PyMT-Dll1+ or PyMT-Dll1− tumor cells into the mammary fat pad (MFP) of syngeneic C57BL/6 mice." (PMID 33462238, 2021). "This conclusion is based on finding similar numbers of UTR, exon, intergenic, intron, and promoter peaks in both Dll1+ and Dll1− tumor cells." (PMID 33462238, 2021). "To complement the in vitro data, we treated Dll1+ tumor cells with doxorubicin, Dll1-blocking antibody, IMD-0354 treatment alone or in combinations." (PMID 33462238, 2021). "To further investigate the distribution of Dll1+ cells during tumor development, we used PyMT-Dll1-GFP mouse model." (PMID 33462238, 2021). "As expected, signatures linked to stem cells, invasion and quiescent cells were enriched in Dll1+ tumor cells, supporting our experimental data that Dll1+ cells have stem-like properties that increase their invasive properties." (PMID 33462238, 2021). "We found that transplanted Dll1+ tumor cells initiated tumor growth before Dll1− tumor cells, suggesting that Dll1+ cells display characteristics of TICs." (PMID 33462238, 2021). "Collectively, our results show that anti-DLL1 Dl1.72 mAb is effective in inhibiting ER+ tumor growth and metastases." (PMID 34439228, 2021). "In limiting dilution assay, Dll1+ tumor cells showed a higher capability (1/2791) to initiate xenograft growth compared to Dll1− tumor cells (1/27,341)." (PMID 33462238, 2021). "Combination treatment blocking NF-kB activation, Dll1 and chemotherapy shows almost complete respone in tumor growth in vivo." (PMID 33462238, 2021). "DLL1-mediated Notch signaling can promote tumor cell proliferation, angiogenesis, and tumor stem cell function." (PMID 34374886, 2021). "This mAb binds to DLL1 protein with a calculated kinetic affinity of 4.78 nM, but not to the other human ligands of the Notch pathway, and recognizes cellular DLL1 in DLL1-overexpressing cells and ER+ BC tumor tissues." (PMID 34439228, 2021). "Remarkably, combination therapy targeting Dll1 ligand and NF-κB pathway shows complete response to the doxorubicin in Dll1+ tumor cells." (PMID 33462238, 2021). "DLL1-induced Notch activation promotes tumor cell proliferation, survival, migration, angiogenesis and BC stem cell maintenance." (PMID 34439228, 2021). "Considering a stringent cut off of >5.5 fold change gene expression in Dll1+ vs. Dll1− tumor cells, we identified a set of 10 genes that are strongly expressed in Dll1+ cells as compared to Dll1− cells." (PMID 33462238, 2021). "The RNA-seq data indicated that Notch target genes are activated in Dll1+ tumor cells compared with Dll1− tumor cells." (PMID 33462238, 2021). "Intriguingly, once Dll1− tumors started growing, they grew faster than Dll1+ tumors, suggesting a higher proliferative potential of Dll1− tumor cells." (PMID 33462238, 2021). "Dll1+ tumor cells also have NF-kB1 specific open chromatin region/enriched peak compared to Dll1− cells." (PMID 33462238, 2021). "Moreover, we found that loss of Dll1 led to a dramatic reduction in hyperplasia in PyMT-Dll1cKO compared to PyMT-Dll1WT mammary glands at 8 weeks, suggesting that loss of Dll1 affects early events in tumorigenesis, potentially by impacting tumor-initiating populations." (PMID 33462238, 2021). "We found that Dll1+ tumor cells increase in K8+ luminal compartment compared to basal cells as tumor progresses from hyperplasia to tumor stage in MMTV-PyMT model." (PMID 33462238, 2021).